TNF (tumor necrosis factor)
Diseases named in the same sentence as TNF in open-access papers (continued):
Sharing a sentence is not in itself a finding about the gene and the disease.
melanoma (continued). "Measurements included LDH, interleukin (IL)-6, IL-1β, IL-17, C-reactive protein (CRP) and tumor necrosis factor (TNF)-alpha as well as tumor markers S100 and melanoma inhibitory activity (MIA)." (PMID 33837821, 2021). "Levels of pro-inflammatory cytokines and chemokines including CXCL10, IFNα, IFNβ, IL-1b and TNFα increased with treatment in the majority of the melanoma tumoursphere lines tested." (PMID 34359633, 2021). "In particular, this pathway sensitizes melanoma cells to TNF-alpha and activates the apoptosis module of the TWEAK pathway in thick non-metastasizing melanomas." (PMID 34638912, 2021). "Tumor Necrosis Factor alpha (TNF-α) is a cytokine that plays a vital role in melanoma tumor control in both mouse and lung cancer." (PMID 34531874, 2021). "Engineered MSC overexpressing TNFα, coinjected with malignant melanoma cells, reduced growth of subcutaneous xenografts." (PMID 33957885, 2021). "Collectively, these data indicate that TNFα was a potent suppressor of the MITF transcription factor and the associated melanoma antigen Melan A, particularly in the transitory and melanocytic melanomas, whereas NGFR and AXL induction were variable." (PMID 34073253, 2021). "Upon adoptive CD8+ T cell transfer, TNFα appeared to be a crucial factor in the incitement of melanoma dedifferentiation, which resulted in immune escape and melanoma relapse." (PMID 34445397, 2021). "To analyze melanoma cell responses to TNFα, we evaluated the accumulation of IκB, an NF-κB inhibitor which is rapidly phosphorylated and degraded in response to TNFα." (PMID 34073253, 2021). "On the other hand, vasculature-targeted low-dose TNF-α has also been shown to activate ECs; stabilize tumor vessels; and enhance anti-tumor immunity in pancreatic neuroendocrine, colorectal, and melanoma tumor models." (PMID 34818534, 2021). "Nevi and thin primary melanomas show little expression of TNF-α, transforming growth factor-β (TGF-β), and IL-8, while a marked-up regulation of cytokines and growth factors can be noticed in thick primary melanomas and metastatic melanomas." (PMID 34944611, 2021). "Melanoma cells were treated with TNF-α in a 3-dimensional culture system, and the changes in the expression of E-cadherin, N-cadherin, vimentin, and fibronectin were assessed." (PMID 33986746, 2021). "TNF promotes melanoma cells to migrate towards and spread along blood vessel endothelial cell surfaces." (PMID 34194957, 2021). "As melanoma remains the textbook example for immunotherapy responsiveness, TNFα targeting studies are most numerous for this cancer type." (PMID 34445397, 2021). "TNF was also involved in de novo expression of MHC class II in melanomas, which results in favoring the accumulation of tumor-specific CD4+ T cells in the tumor microenvironment and local immune response." (PMID 34068679, 2021). "TNFα is abundantly expressed by immune cells upon activation and melanoma cells can respond to TNFα with dynamic phenotypic transitions." (PMID 34073253, 2021). "In melanoma cells, TNFα overexpression accompanied by the secretion of potent cytokine IL6 will be probably able to induce a strong inflammatory response in vivo." (PMID 33957885, 2021). "In parental melanoma cells A375, zafirlukast itself, surprisingly, dramatically increased expression of TNFα mRNA (up to 100 times) and also increased IL6 expression." (PMID 33957885, 2021). "Multiple studies have identified the ability of α-MSH to reduce the expression of adhesion molecules linked to the metastatic potential of melanoma cells including ICAM-1 induced in melanoma cells by TNF-α." (PMID 34068618, 2021). "In the case of melanoma, TNFα is involved in many of the mechanisms known to alter plasticity, leading to tumor escape by increasing adhesion molecules such as fibronectin." (PMID 34604096, 2021).
melanoma (continued). "Prior work has demonstrated that the treatment with recombinant human TNF-α in a B16F10 melanoma mouse model of lung metastasis increased tumor burden and metastatic foci and was associated with increased numbers of pulmonary regulatory CD4+/Foxp3+ T cells." (PMID 33986746, 2021). "Surprisingly, we found a significant increase ILC2 TNF-α production, a potent anti-tumor cytokine known to severely inhibit melanoma growth amongst others." (PMID 34531874, 2021). "For example, melanoma cells cultured in conditions such as hypoxia, glucose and glutamine starvation, presence of inflammatory cytokines such as TNF-α and TGFβ, ultimately switch to an invasive state." (PMID 34604096, 2021). "Although this difference is not completely understood, antifibrotic cytokine tumor necrosis factor (TNF-α) was significantly highly expressed in halo nevus than in melanoma, while fibrogenic cytokines were more frequently expressed in melanoma." (PMID 34575681, 2021). "Tumor necrosis factor alpha (TNFα) is abundantly expressed as a consequence of T cell activation and can have pleiotropic effects on melanoma response and resistance to PD1 inhibitors." (PMID 34073253, 2021). "We had previously identified the expression of CCL20/TNF/VEGFA cytokines by TAMs in a pilot study with cryopreserved human melanoma tissues." (PMID 34439098, 2021). "In an effort to test the generalizability of the mechanism beyond transplantation, we tested the effects of T cell–derived TNF on tumor destruction using the murine B16F1 melanoma model." (PMID 34752416, 2021). "TNFα secreted by macrophages induces dedifferentiation of human melanoma cells, leading to impaired recognition by cytotoxic T lymphocytes specific for melanocytic antigens." (PMID 33540543, 2021). "In contrast to melanoma, only a handful of preclinical studies have explored the potential of TNFα pathway modulating strategies to treat lung cancer with rather contradictory findings." (PMID 34445397, 2021). "In a mouse melanoma model, TNF-α production induced TNFR-1 dependent death of CD8+ T-cells, thus limiting the accumulation of these tumor infiltrating lymphocytes in the tumor microenvironment." (PMID 33920379, 2021). "In an experimental melanoma, it was determined that anti-CTLA-4 treatment increased the production of TNFα associated with T lymphocytes infiltration, which in turn upregulated Ezh2, silencing tumor cell immunogenicity and antigen presentation." (PMID 33540543, 2021). "In a preclinical melanoma model, TNFα, acting through TNFR1, impaired the infiltration of CD8+T lymphocytes into the TME and promoted their activation-induced cell death, facilitating tumor growth." (PMID 33540543, 2021). "Targeted TNF to the melanoma antigen gp75 in combination with a monoclonal antibody of the same specificity augmented the efficacy in syngeneic melanoma models compared to either therapy alone." (PMID 33803078, 2021). "For instance, compared to anti-PD-1 alone, the combination of anti-PD-1 and a TNF/TNFR1 gene defect or TNF blockade had better therapeutic benefit (75% survival versus <20% survival) in melanoma and lung cancer mouse models." (PMID 34367136, 2021). "In contrast, TNFα induced PD-L2 in 21/40 melanoma cell lines, although the fold induction was inconsistent, ranging from 1.5 to 11.1, with a mean fold induction of 2.3." (PMID 34073253, 2021). "Another study showed that ABP-280 (filamin) binds stress-activated protein kinase (SAPK) activator SEK-1, which is the ABP necessary for activating inflammatory TNF-SAPK in melanoma cells." (PMID 34194957, 2021). "In human and canine melanoma cells, 5-aza promotes apoptosis by upregulating the mRNA expression of the tumor necrosis factor-alpha (TNF-α) via the activation of FoxO1 resulting from the inactivation of Akt." (PMID 34418600, 2021).
melanoma (continued). "The upregulation of PD-L2 was independent of melanoma differentiation state; both melanocytic and dedifferentiated melanoma cells showed a similar degree of induction in response to TNFα." (PMID 34073253, 2021). "It was reported that melanoma cells undergo TNF-α-dependent apoptosis after treatments with IL6 and the soluble form of the IL6 receptor, sIL6R." (PMID 34411141, 2021). "We report that TNFα signaling is retained in all melanomas but the downstream impact of TNFα was dependent on the differentiation status of melanoma cells." (PMID 34073253, 2021). "CD37 inhibition suppresses lung metastasis originating from melanoma through the induction of expansion of CD11b+Gr-1hi myeloid cells and enhancing the synthesis of TNF-α and interleukin 1β (IL-1β)." (PMID 32902664, 2021). "In vitro, neutrophil-derived tumor necrosis factor (TNF) stimulates melanoma cell migration, suggesting that TNF is one of the factors related to neutrophil-induced metastasis." (PMID 34674757, 2021). "Tüting’s team highlighted the role of TNFα in the enhancement of endothelial cell sprouting and promoted the pericyte-like expansion of co-cultured melanoma cells along such endothelial outgrowths." (PMID 34604096, 2021). "In contrast, the upregulation of AXL by TNFα was variable and only observed in 6/40 melanoma cell lines tested." (PMID 34073253, 2021). "It was later detailed that TNF-α kills tumor cells through enhancement of tumor oxidative stress in melanoma cells." (PMID 34531874, 2021). "Senescence induction was observed also in parental melanoma cells treated with recombinant human TNFα protein." (PMID 33957885, 2021). "In cultured B16F10 melanoma cells, TNF-α reduced the expression of TYR and TRP1 and TYR activity in a dose-dependent manner." (PMID 34603597, 2021). "To test this, we first cultured B16 melanoma cells in the bottom well of a 0.4μm Transwell plate with either a mouse neutralizing TNF-α antibody or the isotype." (PMID 34531874, 2021). "Altogether, our data suggest that the B16 melanoma tumor microenvironment induces phosphorylation of the NFκB pathway in PD-1 deficient pulmonary ILC2s, potentially stimulating ILC2 TNF-α production." (PMID 34531874, 2021). "Given toxicity concerns, TNF-α has been deemed unsafe to administer systemically but has shown some efficacy in isolated limb perfusion in melanoma and sarcoma, where it has ≥80% objective response rates." (PMID 34063789, 2021). "TNFα also promotes melanoma dedifferentiation by suppressing the expression of the microphthalmia-associated transcription factor (MITF), a master regulator of the pigmentation pathway and melanocytic antigens, including the TRP1, DCT and MLANA genes." (PMID 34073253, 2021). "In another study, crocin (250 and 500 μg/kg) attenuated VEGF, MMP-2, and MMP-9 expressions and TNF-α and IL-6 levels while it elevated IL-10 level in melanoma metastatic model in C57BL/6 mice." (PMID 34956439, 2021). "This suggests the existence of the feedback loop of OPN and IL-6 in which the hormone acts both on melanoma, stimulating its proliferation, and on adipocytes, enhancing IL-6 and TNF-α synthesis." (PMID 34068679, 2021). "We examined TNFα effects on melanoma differentiation by analyzing the accumulation of the key marker proteins MITF, Melan A, AXL and NGFR in the 40 melanoma cell lines." (PMID 34073253, 2021). "Overexpression of MnSOD promotes the survival of melanoma cells exposed to the cytostatic and cytotoxic effects of cytokines (interleukin-1, IL-1; tumor necrosis factor, TNF), chemotherapeutic agents (doxorubicin, mitomycin C), and ionizing irradiation." (PMID 34943045, 2021).
melanoma (continued). "Of note, previous studies have shown the bifurcated functions of TNFα on melanoma pathogenesis, which is possibly determined by the source and the dosage of TNFα for the stimulation of melanoma cell." (PMID 34924562, 2021). "Excitingly, a relatively high percentage of ILC2s cultured with either the antibody or the isotype produced TNF-α, suggesting the B16 melanoma context from which they originated primed the cells for TNF-α production." (PMID 34531874, 2021). "In order to explain the diverse cellular response to TNFα, we engineered melanoma and colorectal carcinoma cell lines stably overexpressing this cytokine." (PMID 33957885, 2021). "The safety of the triple combination of ipilimumab, nivolumab and an antibody inhibiting TNF-α (infliximab or certolizumab) is being studied in a phase I clinical trial in advanced melanoma (NCT03293784)." (PMID 34063789, 2021). "In this study, we examined the influence of TNFα on markers of melanoma dedifferentiation, antigen presentation and immune inhibition in a panel of 40 melanoma cell lines." (PMID 34073253, 2021). "IL-6 and TNF-α secreted by adipocytes block miR-211 expression, leading to the elevated production of TGFβ receptors and, therefore, a phenotypic switch of melanoma from the proliferative to the highly invasive state." (PMID 33430277, 2021). "Rather than the number, size, or location of TAM, quantitative assessment of CCL20, TNF, and VEGFA cytokine content was associated with strong prognostic significance in primary melanoma." (PMID 34439098, 2021). "Whereas, miR-9 shows apositive regulatory effect on TNF expression in D10 and A375 melanospheresand melanoma patient samples." (PMID 34308569, 2021). "Studies revealed that while proinflammatory cytokine TNF-α increases the expression of integrins in HBL melanoma cells, α-MSH treatment leads to a reduction in integrin expression." (PMID 34068618, 2021). "Similar results have also been observed in melanoma cell lines where 9 out of 16 birinapant resistant tumors were dramatically sensitized to birinapant-mediated killing with the addition of TNF." (PMID 32053868, 2020). "For instance, when co-expressed with TIM-3, PD-1 decreases the secretion of various pro-inflammatory cytokines, such as IL-2, IFN-γ, and TNF, and results in T cell tolerance towards tumor cells in acute myelogenous leukemia, colon adenocarcinoma, and melanoma." (PMID 31968651, 2020). "The expression of IL-12 and TNF-α in B16F10 melanoma was very low; a few cells were found in the GET pMCAM IR group." (PMID 32204304, 2020). "We and others demonstrated the key role of growth factors such as FGF-2, PDGF, and TNF-α in controlling melanoma growth and melanoma aggressiveness." (PMID 33302400, 2020). "Our group has shown that TNFα-stimulated human DCs pulsed with a melanoma cell lysate can establish functional GJ-mediated intercellular communications and promote melanoma antigen transfer between ex vivo produced DCs." (PMID 32466338, 2020). "In the tumor stroma, MAPK inhibition enhances the recruitment of tumor-associated macrophages that, through TNFα release, increase the expression of MITF in melanoma cells." (PMID 32466585, 2020). "Studies in the 1990s demonstrated that perfusion of TNF in isolated limbs of patients presenting with melanoma or sarcoma induces anti-tumour effects with limited toxicity." (PMID 32365592, 2020). "Consistent with this, nivolumab+ipilimumab in combination with the anti-TNF-α antibody certolizumab has been studied in advanced melanoma in clinical trial (NCT03293784)." (PMID 33276788, 2020). "For example, molecular engineering to direct TNF towards tumour neo-vasculature can increase immune infiltration and impairs the growth of established melanoma and prostate tumours." (PMID 32365592, 2020).
melanoma (continued). "IGF1R expression has been related to both the intrinsic mitochondrial pathway, as observed in colon cancer cells, and the TNF-TRAIL pathway in melanoma cells." (PMID 32899449, 2020). "For this purpose, melanoma cell lines (A375 and A375R) were treated with IFNγ (50 ng/ml) and TNF- α (10 ng/ml)." (PMID 32117720, 2020). "Overall, these results suggest that Lsp1 overexpression in T cells promotes melanoma growth through downregulation of TNF-α+ and IFN-γ+ production by CD8+ T cells, in addition to a marked decrease in infiltrated CD8+ T cells." (PMID 33020243, 2020). "Particularly interesting is the strong correlation of IL-6 to TNF-α in the melanoma samples; these two molecules are known to control the ability to evade the immune system control in a PDL-1-dependent manner." (PMID 33302400, 2020). "While TNF has pro-survival effects on melanoma cells, enhancing invasion and migration potential, SMs can convert this advantage to a liability." (PMID 32053868, 2020). "In a recent study, CT induced apoptosis in melanoma cell lines and increased the sensitivity of A375 cell line to tumor necrosis factor (TNF)–related apoptosis-inducing ligand (TRAIL), which further led to the enhancement of cell death in melanoma cells." (PMID 32265690, 2020). "For instance, GM-CSF was included in anti-melanoma vaccination efforts, and TNFα was previous a part of anti-melanoma clinical strategies." (PMID 32085661, 2020). "Accordingly, analysis of a previously published dataset shows that PTGS2 and MITF are regulated in an inverse manner after TNFα treatment in melanoma cells." (PMID 32978520, 2020). "The first demonstration of melanoma cell eradication in a neoadjuvant setting employed polylactic acid microspheres (PLAMs) loaded with IL-12 or TNF-a in a B16 melanoma mice model." (PMID 32708968, 2020). "Reflecting the inflammatory microenvironment by supplementation of IFN-γ or TNF-α to melanoma cell culture has provoked cell dedifferentiation, and was associated with increased susceptibility to ferroptosis induction." (PMID 32340261, 2020). "NKTR-214 administration increased the levels of both IFN-γ and TNF-α in B16.F10 tumor tissue and in human melanoma and RCC tumors." (PMID 32005826, 2020). "Consistent with its uncertain role in melanoma, TNF-α plays a dual role, either acting as a cytotoxic cytokine or favoring a tumorigenic inflammatory microenvironment." (PMID 33202705, 2020). "TAK1 inhibition sensitized melanoma cells to apoptosis induced by a combination of TNF-α and TRAIL, indicating that TAK1 regulated apoptosis-related role of RIPK1 in melanoma." (PMID 32340261, 2020). "A combination of MAPK pathway inhibition with IκB kinase (IKK) inhibitors improves the therapeutic response, diminishing MITF expression in melanoma cells and blocking TNFα activity in tumor stroma." (PMID 32466585, 2020). "Based on results in experimental melanoma, it is shown, by a mathematical model, that resistances to anti-PD-1 can be significantly reduced by combining it with anti-TNF-α." (PMID 32310956, 2020). "It is possible that this unexpected improvement of efficacy in vivo compared with in vitro, is due to elevated levels of TNF in the microenvironment of melanoma lesions due to chronic inflammation." (PMID 32053868, 2020). "Vitamin D inhibited IL-1 and TNF-α protein and mRNA levels, suggesting transcriptional mechanism; and its effectiveness in inhibiting inflammation in melanoma cells." (PMID 32150881, 2020). "Based on this evidence, an ongoing clinical trial was launched in melanoma patients, combining nivolumab + Ipilimumab + the anti-TNFα certolizumab." (PMID 32391269, 2020). "Regarding inter‐DCs’ relationship, positive correlations between TNFα‐producing cDC2s and pDCs observed in HD blood were lost in melanoma patients." (PMID 33282290, 2020).